COMT (catechol-O-methyltransferase)
Diseases named in the same sentence as COMT in open-access papers (continued):
Sharing a sentence is not in itself a finding about the gene and the disease.
depression (continued). "In this study, we estimated the contribution of SLC6A4 (5HTT), HTR1A, HTR2A, HTR1B, SLC6A3 (DAT1), DRD4, DRD2, COMT, and BDNF genes to the suicidal behavior and severity of symptoms of depression and anxiety in the East-Slavic population of Russia." (PMID 34199792, 2021). "This study aims to estimate the contribution of 11 polymorphisms in the genes SLC6A4 (5HTT), HTR1A, HTR2A, HTR1B, SLC6A3 (DAT1), DRD4, DRD2, COMT, and BDNF to suicidal behavior and severity of symptoms of depression and anxiety in the Russian population." (PMID 34199792, 2021). "Individuals (154 female and 87 male) with major depression disorder (MDD) with Met/Met, Met/Val, and Val/Val COMT genotypes differed in their response to bupropion treatment in terms of PHQ‐9 scores." (PMID 32459054, 2020). "related genes of dopamine system (DRD2, COMT), HPA axis system (CRHR1), and immune system (IL-1β SNP), can also interact with the environment to affect the occurrence of depression in a gender-specific manner." (PMID 33193645, 2020). "Furthermore, the interaction effect between the COMT genotype and group for the WMI after controlling for depression scores also remained significant (F (2160) = 4.051, p = 0.019, η2p = 0.048)." (PMID 32752289, 2020). "Our recent published work also revealed a non-linear modulation of the interaction between the COMT gene and depression on brain function." (PMID 28959185, 2017). "Among these, MAOA, COMT, TPH1, and TPH2 have been reported to be associated with depression, but a recent genome-wide association study found no significant genome-wide association, and the best candidates did not involve these pathways." (PMID 21827647, 2011). "The catechol-O-methyltransferase (COMT) gene contains a functional polymorphism, Val158Met, which has been linked to anxiety and depression, but previous results are not conclusive." (PMID 18578865, 2008). "The non-significant findings seem to apply to COMT gene variation in anxiety as well as depression." (PMID 39202218, 2024). "Finally, as the analysis carried out in the study showed, the influence of the COMT genotypes on the neuropsychological outcomes was independent of clinical symptoms (i.e., pain, depression and anxiety)." (PMID 32752289, 2020). "Notably, pain severity was only significantly higher in participants homozygous for COMT rs4680 “GG” and heterozygous for “GA” genotypes than participants homozygous for “AA” genotype in the subgroup of PD patients without depression." (PMID 28740224, 2017). "Furthermore, the pain severity was significantly higher in participants homozygous for COMT rs4680 “GG” and heterozygous for “GA” genpotypes than participants homozygous for “AA” genotype in the subgroup of PD patients without depression." (PMID 28740224, 2017). "Notably, pain severity was only significantly higher in participants homozygous for COMT rs4680 “GG” and heterozygous for “GA” genpotypes than participants homozygous for “AA” genotype in PD patients without depression." (PMID 28740224, 2017). "After controlling for HAD anxiety and depression scores, the interactions between EAL scores and ADRAβ2 rs1042717 and COMT rs174697 were not statistically significant." (PMID 26288143, 2015).
Anxiety (94 papers, 2006 to 2026). Intense feelings of nervousness, tension, or panic often arise in response to interpersonal stresses. "COMT variants have also been associated with myofascial pain and disc displacement as well as anxiety." (PMID 39482899, 2025). "There is a significant interaction between gambling disorder and amphetamine use disorder, and the COMT gene rs4680 polymorphism in the outcome score level of anxiety as a trait." (PMID 38540358, 2024). "The 5HTTLPR gene is strongly associated with anxiety sensitivity and anxiety responses, and the COMT gene is strongly associated with the loss of mood and pain." (PMID 39590895, 2024). "There is a significant interaction between gambling disorder and amphetamine use disorder, and the COMT gene rs4680 polymorphism in the outcome score level of anxiety as a state." (PMID 38540358, 2024). "In humans, a functional polymorphism located in exon 4 of the COMT gene (Val158Met) has garnered significant scientific attention due to its counterbalancing effect on emotional resilience, stress, anxiety and cognition." (PMID 38318385, 2024). "This study aimed to investigate the association between the pain candidate genes 5-HTTLPR and COMT and anxiety in Japanese ballet dancers." (PMID 39590895, 2024). "The findings suggest an association between the COMT polymorphism and specific expressions of anxiety among women in the Australian population." (PMID 39590895, 2024). "The level of anxiety in parturients differed with regard to the polymorphism of the COMT gene, but only in parturients with analgesia." (PMID 37834942, 2023). "An interesting variant in this context is the COMT Val108/158Met polymorphism, which has been associated with anxiety susceptibility and anxiety-related traits." (PMID 37637902, 2023). "COMT gene variants are engaged in a number of psychological roles, e.g. cognition, anxiety, and stress response." (PMID 38053955, 2023). "Lower pain perception at the end of delivery remained significantly associated with analgesia, with control of potential influencing factors (age, height, and parity of the mother; sex and weight of the baby; the level of anxiety; COMT polymorphism)." (PMID 37834942, 2023). "We investigated the association of the COMT polymorphism with anxiety as a personality trait and pain perception in parturients with inhaled nitrous oxide." (PMID 37834942, 2023). "Our study showed that the COMT gene polymorphism GA was correlated with the level of anxiety and pain among parturients." (PMID 37834942, 2023). "The aim of this study was to investigate the association between the COMT polymorphism, anxiety trait, and pain perception in labouring women." (PMID 37834942, 2023). "According to a previous study, compared with single SNP analysis, haplotype analysis improved the statistical power for the moderating effect of COMT haplotypes on the association between antenatal maternal anxiety and neonatal cortical morphology." (PMID 38666110, 2023). "Presence of the COMT rs4680 (val158met) major allele has been reported to be associated with increased chronic pain and anxiety in IBS patients." (PMID 35207633, 2022). "This study explored the effect of COMT polymorphism on fentanyl and dexmedetomidine in labor anxiety and analgesia." (PMID 35346044, 2022). "First, we considered the associations between the COMT rs4680 gene polymorphism and personality dimensions and anxiety." (PMID 36292653, 2022). "Catechol-O-methyltransferase (COMT) polymorphism is associated with anxiety symptoms in breast cancer patients." (PMID 34284736, 2021). "COMT rs4680, as well as interactive effects between this gene and environmental adversities, has been associated with anxiety and panic symptom." (PMID 32618128, 2020).
Anxiety (continued). "Fourth, the association between COMT functional polymorphisms and anxiety, though grounded in theoretical and experimental work, has never been conclusively demonstrated in the context of health anxiety or responses to the threat of infection." (PMID 32879833, 2020). "Next, we discuss the association between the Val158Met COMT polymorphism and anxiety manifestations more specifically." (PMID 31156495, 2019). "Results and comparison of the genetic models for the COMT polymorphism on scale MAQ D – Anxiety Toward Mathematics." (PMID 31156495, 2019). "The COMT Val158Met polymorphism, which affects dopamine levels in the prefrontal cortex, has been associated with anxiety manifestations." (PMID 31156495, 2019). "The COMT Val158Met polymorphism has been implicated in anxiety manifestations in males and females (Hosák, 2007; Harrison and Tunbridge, 2008)." (PMID 31156495, 2019). "More recent research also supports a nuanced picture of the association between COMT genotypes and anxiety manifestations." (PMID 31156495, 2019). "We sought to determine the role of functional genetic variation in COMT, which encodes catechol-O-methyltransferase, in the association between maternal prenatal anxiety and child symptoms of ADHD and working memory." (PMID 28614354, 2017). "Genetic variation in catechol-O-methyltransferase (COMT) is associated with anxiety, personality, pain, and response to placebo treatment." (PMID 25722948, 2015). "The association of LVA variants in females to a catechol-o-methyltransferase (COMT) gene and to anxiety and alcoholism is discussed in a later section (see “Electrophysiological Measures as Endophenotypes for Alcoholism”)." (PMID 26259089, 2015). "A significant main effect of COMT met alleles (β = −32.5, SE 14.1, P = 0.0212) was qualified by COMT met alleles × conscientiousness (β = 0.73, SE 0.3, P = 0.0042) and COMT met alleles × anxiety interactions (β = −0.42, SE 0.16, P = 0.0078)." (PMID 25722948, 2015). "COMT facilitates dopamine breakdown; hence, when mutations of COMT are suspected, patients may be linked to poor antidepressant responses, psychosis, anxiety, and addiction." (PMID 41584105, 2026). "Therefore, our study aimed to investigate the relationship between polymorphisms in pain candidate genes (5-HTT and COMT) and the ballet dancers’ anxiety and mood throughout a usual practice day and performance day." (PMID 39590895, 2024). "People with the slow A allele of the COMT gene (rs4680 polymorphism) may face a higher risk of anxiety, neuropsychiatric issues, and heightened sensitivity to environmental toxins." (PMID 39148948, 2024). "The COMT gene polymorphism was associated with pain perception and anxiety among parturients." (PMID 37834942, 2023). "The level of anxiety differed considering the polymorphism of the COMT gene." (PMID 37834942, 2023). "Presently, it is believed that COMTval158met gene polymorphism can change the COMT activity; COMTval158met gene mutation reduces COMT activity, leads to reduced catecholamine degradation in vivo, increases catecholamine content, and even leads to an abnormal anxiety state." (PMID 35346044, 2022). "Then, the relationship between labor anxiety, analgesia, and COMT polymorphism was analyzed." (PMID 35346044, 2022). "The aim of the study: The aim of this study was to investigate the association of the rs4680 polymorphism of COMT with personality dimensions and anxiety in patients addicted to stimulants other than cocaine (F15 according to WHO ICD-10 nomenclature) in the case of examined patients amphetamine." (PMID 36292653, 2022). "Finally, reporting a more severe insomnia and having the COMT Met/Met genotype were significantly associated with a higher anxiety score." (PMID 34330229, 2021).
Anxiety (continued). "These preliminary results suggest that there may be a relationship between the COMT Val158Met or rs4680 functional polymorphism and the impact of COVID-19 across nations, which could plausibly be mediated by maladaptive anxiety-related behaviours." (PMID 32879833, 2020). "Future research should investigate whether the heterosis model of the interaction among sex, COMT Val158Met polymorphism and MA is generalizable to other forms of anxiety." (PMID 31156495, 2019). "In the final two sections, we are going to discuss: (a) the mechanisms of estrogen effects that may contribute to increase the levels of MAQ D – Anxiety Toward Mathematics in homozygous girls; and (b) the role of heterosis in the COMT Val158Met polymorphism." (PMID 31156495, 2019). "COMT Val158Met polymorphism and anxiety have also been associated." (PMID 31156495, 2019). "In the Introduction, we will present the following topics: (a) sex differences in MA; (b) behavioral genetics of MA; (c) genetic models; (d) COMT Val158Met polymorphism and cognition; (e) COMT Val158Met polymorphism and anxiety; (f) outline of the present study." (PMID 31156495, 2019). "But in this regard it is still important to note that for several anxiety related traits, gender specific effects of the COMT Val158Met polymorphism with especially pronounced results in females (Met allele associated with higher anxiety related traits) have been observed." (PMID 30127727, 2018). "A report from Singapore on 146 neonates indicated that the association between prenatal maternal anxiety and neonatal cortical morphometry was moderated by genetic variation in COMT, with increased thickness of the ventrolateral prefrontal cortex observed in neonates with the val allele." (PMID 28614354, 2017). "Relevant to the current study is evidence that the well-documented association between prenatal maternal anxiety or stress and child outcome cited above may be moderated by the child’s COMT genotype." (PMID 28614354, 2017). "For example, the counterintuitive selection for low activity COMT haplotypes associated with high pain, anxiety, and stress response may be driven by a gain of cognitive function related to higher dopamine and norepinephrine levels." (PMID 19365560, 2009). "Considering the pleiotropic nature of COMT (rs4680), G carriers could possess greater stress resilience and reduced anxiety in competitive environments and be at lower risk of experiencing concussions but also be at risk of poorer cognitive function post-concussion." (PMID 35627205, 2022). "We hypothesised that patient's self‐reported pain levels during fixed orthodontic treatment are influenced by clinical factors, psychological factors, such as anxiety and pain catastrophising, as well as certain single nucleotide polymorphisms (SNP) of the COMT, HTR2A and NR3C1 genes." (PMID 34273191, 2021). "In general, studies with children reveal that the COMT Val158Met polymorphism may act as a moderator between different kinds of anxiety manifestations in hetero-report measures and environmental stressors such as early emotional trauma and maternal anxiety." (PMID 31156495, 2019). "However, while some, notably associations between COMT Val158Met and dopamine-dependent cognitive function and anxiety-related phenotypes, show promise, non-replications exist; thus, associations between COMT and neuropsychiatric phenotypes remain controversial." (PMID 27388330, 2016). "Studies in mice have shown that homozygous COMT-knockout females develop increased anxiety in a light-dark model compared to COMT-knockout males." (PMID 38540358, 2024). "The results indicate that 5-HTTLPR and COMT play a crucial role in dancers’ anxiety and mood during pain (ps < 0.05)." (PMID 39590895, 2024). "We found that 5-HTTLPR and COMT played a crucial role in the background of anxiety and mood over a long period from daily practice to performance day." (PMID 39590895, 2024).
Anxiety (continued). "We also showed an interaction between anxiety as a trait and the rs4680 genotypes of the COMT gene and conscientiousness and the rs4680 genotypes of the COMT gene." (PMID 38540358, 2024). "This study investigated the relationship between candidate genes, 5-HTT and COMT, and anxiety when ballet dancers with pain are placed under stress." (PMID 39590895, 2024). "The present study investigates the existence of anxiety and pain perception in relation to the COMT (catechol-O-methyltransferase) gene polymorphism in labouring women (during “natural” childbirth) with or without inhaled analgesia." (PMID 37834942, 2023). "In FM rats, reduced anxiety was associated with increased hippocampal expression of BDNF and COMT genes with a simultaneous increase in DAT gene expression." (PMID 36498900, 2022). "Before and after labor analgesia, the genotype of COMT in the blood from two groups was detected, and the situation of labor anxiety and analgesia was analyzed." (PMID 35346044, 2022). "Another gene that has been studied for its role in moderating response to stress and related anxiety and mental health disorders is catechol-O-methyltransferase (COMT)." (PMID 35377919, 2022). "Another study suggested that BDNF rs6265 had a significant interaction effect with Catechol-O-methyltransferase gene (COMT) polymorphism to neuroticism and anxiety trait in PD patients, instead of healthy control subjects." (PMID 35815047, 2022). "A functional polymorphism of the catechol O-methyltransferase (COMT) gene, designated rs4680 or Val158Met, has been associated with anxiety-related behaviours and the so-called "worrier" phenotype." (PMID 32879833, 2020). "No conclusions or specific dose recommendations can be made at this time, but due to the documented co-prevalence of anxiety and pain disorders, particularly in patients with low COMT activity, further research is warranted." (PMID 33276542, 2020). "The interaction between sex and the COMT Val158Met genotype in MAQ D – Anxiety Toward Mathematics was significant under the heterosis model." (PMID 31156495, 2019). "Six of the 11 reported studies investigated the interaction between sex and COMT influences on anxiety." (PMID 31156495, 2019). "Several sets of analyses were conducted to examine the robustness and specificity of the prenatal anxiety X child COMT genotype interaction in the prediction of markers of neurodevelopment." (PMID 28614354, 2017). "Further work is required to determine if maternal prenatal anxiety influences the epigenetic regulation of COMT expression." (PMID 28614354, 2017). "It is particularly notable that our analyses of more than ten years’ of data from this large community sample is consistent with prior work on COMT moderating a prenatal anxiety exposure based on smaller and/or younger samples." (PMID 28614354, 2017). "The reliability of the prenatal maternal anxiety X child COMT genotype was also suggested when we applied an analytic approach suggested by Keller." (PMID 28614354, 2017). "Data from COMT transgenic mice, in which genetic and environmental variability can be controlled and experimentally manipulated, are therefore invaluable for clarifying relationships between COMT and anxiety." (PMID 27388330, 2016). "Our results show that these mice have little cognitive or anxiety phenotype on the tests used, but that genotype differences emerge following pharmacological COMT inhibition." (PMID 27388330, 2016). "We compared performance of COMT-Met mice with that of their wild-type littermates on cognitive and anxiety tasks that have previously been shown to be sensitive to the effects of COMT." (PMID 27388330, 2016). "The COMT knockout mouse shows increased anxiety and an exaggerated reactivity to acute stress, compared with wild-type animals." (PMID 27388330, 2016).